NSUN2 (NOP2/Sun RNA methyltransferase 2)
Diseases named in the same sentence as NSUN2 in open-access papers (continued):
Sharing a sentence is not in itself a finding about the gene and the disease.
lung carcinoma (11 papers, 2020 to 2026). "This association emphasizes the complex interplay between NSUN2, m5C modification and lncRNA regulation in the context of lung cancer, necessitating further exploration to uncover their precise mechanistic contributions." (PMID 40008496, 2025). "Notably, the heightened expression of H19 lncRNA, observed in numerous adult malignant lung cancer tumours, has been linked to NSUN2‐mediated m5C modification, resulting in H19 stabilisation and subsequent pro‐oncogenic effects." (PMID 40008496, 2025). "In lung cancer, NSUN2 mediates m5C methylation of circRREB1, which is recognized by the reader protein ALYREF to facilitate its nuclear export." (PMID 41522342, 2026). "In lung cancer, NSUN2-mediated m5C modification promoted mRNA stability of ME1, GLUT3, and CDK2, leading to metabolic reprogramming and cell cycle changes." (PMID 41462962, 2025). "By querying data from The Cancer Genome Atlas (TCGA) database, we found that NSUN2 is highly expressed in lung cancer tissues and that patients with high NSUN2 expression have a poorer prognosis than those with low NSUN2 expression." (PMID 40653497, 2025). "Additional inquiries are warranted to unravel the plausible implications of m5C modification in the progression of lung cancer, particularly the potential contributions of NSUN2, potentially through interactions with lncRNAs." (PMID 40008496, 2025). "Another study had revealed that silencing NSUN2 in lung cancer led to significant downregulation of EGFR expression." (PMID 40156167, 2025). "Research indicates that high expression of NSUN2 leads to resistance to gefitinib and promotes recurrence of lung cancer tumors." (PMID 40370440, 2025). "Cell counting kit (CCK)-8 assays were then conducted to determine the role of NSUN2 in the growth of lung cancer cells." (PMID 38403250, 2024). "In this context, our data proposes a model where NSUN2 regulates the ferroptosis process in lung cancer cells through an m5C-YBX1–dependent manner and acts as a promoter in advancing lung cancer progression." (PMID 38403250, 2024). "As demonstrated in the CCK8 assays, suppressing NSUN2 reduced the viability of lung cancer cells compared to their respective controls over time." (PMID 38403250, 2024). "NSUN2 also has a potential prognostic value in other cancers, such as lung cancer, ovarian cancer, and head and neck squamous cell carcinoma." (PMID 33928086, 2021). "Knockdown of NSUN2 can overcome the intrinsic resistance of lung cancer cells to gefitinib." (PMID 40370440, 2025). "Furthermore, transwell assays indicated that the number of lung cancer cells that migrated through the membrane and their invasive capacity was substantially augmented in the NSUN2 overexpressed groups." (PMID 38403250, 2024). "In conclusion, our findings point to a potential therapeutic strategy for combatting this devastating disease, suggesting that NSUN2 could serve as a prognostic biomarker and therapeutic target in future lung cancer treatments." (PMID 38403250, 2024). "Mechanistic studies show that NSUN2 regulates the m5C modification of QSOX1, and YBX1 enhances QSOX1 translation in an m5C-dependent manner, thereby promoting resistance to EGFR-mutant lung cancer." (PMID 40370440, 2025). "Most recently, a pan-cancer analysis of RNMTs has shown that alterations to NSUN2 are common in lung cancer, although this was not followed up in more detail." (PMID 32708015, 2020).
non-small cell lung carcinoma (11 papers, 2023 to 2026). A group of at least three distinct histological types of lung cancer, including non-small cell squamous cell carcinoma, adenocarcinoma, and large cell carcinoma. "Moreover, high NSUN2 expression has been linked to resistance to gefitinib and tumor recurrence in non-small-cell lung cancer." (PMID 41463199, 2025). "In non-small cell lung cancer NSUN2 and its reader protein ALYREF are upregulated in tumor cells and enhance PD-L1 mRNA stability through m5C modification, leading to PD-L1 overexpression." (PMID 41194917, 2025). "Methylated- RNA immunoprecipitation (MeRIP)-qPCR assay results demonstrated that the m5C level of NRF2 mRNA was higher when NSUN2 was overexpressed in non-small-cell lung cancer (NSCLC) cells." (PMID 41462962, 2025). "In non-small cell lung cancer (NSCLC), both NSUN2 and its m5C reader protein ALYREF are significantly upregulated and contribute to tumor cell proliferation and progression." (PMID 41256859, 2025). "In non-small cell lung cancer (NSCLC), aberrant m5C hypermethylation mediates the resistance to gefitinib via the NSUN2/YBX1/QSOX1 axis." (PMID 38654314, 2024). "NSUN2 knockdown reduces m5C modification and stability of PD-L1 mRNA, enhancing CD8+ T cell-mediated antitumor immunity, demonstrating that the NSUN2/ALYREF/PD-L1 axis directly mediates immunosuppression via m5C modification and drives non-small cell lung cancer progression." (PMID 41194917, 2025). "In non-small-cell lung cancer, the NSUN2/ALYREF axis deposits m5C and promotes nuclear export/stability of PD-L1 mRNA, increasing PD-L1 abundance and facilitating T-cell evasion; perturbing NSUN2 or ALYREF reduces PD-L1 and restores antitumor immunity in mouse and human systems." (PMID 41280938, 2025).
gallbladder carcinoma (10 papers, 2020 to 2025). "For instance, in gallbladder cancer, silencing NSUN2 inhibits the proliferation and tumor formation of gallbladder cancer cells." (PMID 40370440, 2025). "Silencing of NSUN2 inhibits GBC cell proliferation and tumorigenesis, whereas overexpression of NSUN2 promotes gallbladder cancer cell growth." (PMID 40370440, 2025). "High expression of NSUN2 was found to occur in gallbladder carcinoma (GBC), and silencing of NSUN2 repressed GBC cell proliferation and tumorigenesis both in vitro and in vivo via an interaction with Ribosomal Protein L6 (RPL6)." (PMID 32708015, 2020). "NSUN2 promoted gallbladder carcinoma cell growth and colony formation by upregulating RPL6." (PMID 41462962, 2025). "NSUN2 is also highly expressed in gallbladder carcinoma tissues and cell lines." (PMID 41462962, 2025). "The highly expressed NSUN2 closely interacts with RPL6 to promote the proliferation and tumorigenesis of gallbladder cancer cells in both in vitro and in vivo." (PMID 33928086, 2021).
head and neck squamous cell carcinoma (10 papers, 2020 to 2025). A squamous cell carcinoma that arises from any of the following anatomic sites: lip and oral cavity, nasal cavity, paranasal sinuses, pharynx, larynx, and salivary glands. "In head and neck squamous cell carcinoma (HNSCC), NSUN2 is significantly upregulated in tumor tissues and is associated with poor prognosis." (PMID 41256859, 2025). "In head and neck squamous cell carcinoma (HNSCC), NSUN2 is negatively correlated with M2 macrophage polarization and T cell activation." (PMID 40370440, 2025). "In head and neck squamous cell carcinoma (HNSCC), the expression of NSUN2 is significantly upregulated, which correlates with shorter OS as well as the expression of cell cycle checkpoint-related genes." (PMID 35562754, 2022). "In head and neck squamous cell carcinoma (HNSCC), NSUN2 expression is significantly upregulated, which may be associated with mitochondrial function and cell cycle checkpoint-related genes." (PMID 40370440, 2025). "In head and neck squamous cell carcinoma (HNSCC), the combination of NSUN2 expression and T-cell activation correlates with patient survival regardless of the HPV status, indicating that NSUN2 may serve as a potential biomarker for immune-checkpoint blockade." (PMID 35365216, 2022).
ovarian carcinoma (10 papers, 2020 to 2026). A malignant neoplasm originating from the surface ovarian epithelium. "NOP2/Sun RNA methyltransferase family member 2 (NSUN2) is the main methyltransferase in mRNA m5C modification and implicated in ovarian cancer." (PMID 41326692, 2026). "The subcutaneous tumorigenesis assay revealed that E2F1 knockdown reduced the volume and weight of tumors formed from ovarian cancer cells, which phenocopied the effect of NSUN2 deficiency." (PMID 38424195, 2024). "NSUN2 deficiency prevented the formation of metastatic foci by ovarian cancer cells in the peritoneal cavity." (PMID 38424195, 2024). "To determine the tumorigenic function of NSUN2 in ovarian cancer, we performed gain- and loss-of-function assays in ovarian cancer cells." (PMID 38424195, 2024). "m5C modification of E2F1 mRNA directs its regulation of target gene expression, which is implicated in the NSUN2-mediated tumor-promoting effect on ovarian cancer." (PMID 38424195, 2024). "To further validate the implication of E2F1 in NSUN2-mediated ovarian cancer progression, we performed rescue assays in NSUN2-deficient ovarian cancer cells." (PMID 38424195, 2024). "Overexpression of NSUN2 was associated with higher rate of overall and disease progression-free survival in ovarian cancer patients, suggesting that NSUN2 was a cancer suppressor for ovarian cancer." (PMID 32393790, 2020). "To further pinpoint the mechanism of gene regulation mediated by NSUN2, we used the odds ratio (OR) to evaluate the correlations between the m5C-hypermethylated RNAs or NSUN2-bound transcripts and the differentially expressed genes (DEGs) in NSUN2-deficient ovarian cancer cells." (PMID 38424195, 2024). "Loss of NSUN2 strongly inhibited the growth, migration, and invasion of ovarian cancer cells." (PMID 38424195, 2024). "The meRIP assay showed that m5C modification of PARP10 mRNA was reduced when NSUN2 was knocked down in ovarian cancer cells." (PMID 41326692, 2026). "Subsequent investigations revealed that ALYREF promotes platinum resistance in ovarian cancer cells by activating the Wnt/β-Catenin pathway via the NSUN2/ALYREF/LGR4 signaling axis." (PMID 41345330, 2025). "At the same time, the downregulation of KPNA2 level will irremediably down-regulate the expression of NSUN2, thereby inhibiting ovarian cancer cell growth." (PMID 41413017, 2025). "The NSUN2 amplification frequency (approximately 7%) is lower than the frequency of NSUN2 RNA upregulation (15%) in ovarian cancer, according to TCGA ovarian cancer datasets." (PMID 38424195, 2024). "m5C modification at 16,536 sites within 6,192 RNAs was reduced upon NSUN2 knockdown, and these m5C-modified sites were identified as m5C hypermethylated sites in ovarian cancer cells." (PMID 38424195, 2024). "The Transwell assay revealed that NSUN2 overexpression promoted the migration and invasion of these ovarian cancer cells." (PMID 38424195, 2024). "According to the Oncomine database, NSUN2 was also amplified and upregulated in ovarian cancer tissues compared with normal ovarian surface epithelium (NOSE) tissues." (PMID 38424195, 2024). "We integrated the E2F1 ChIP-seq and RNA-seq data for NSUN2 in ovarian cancer cells and found that 120 genes were potential targets of both NSUN2 and E2F1." (PMID 38424195, 2024). "Consistently, according to several GEO ovarian cancer datasets, NSUN2 expression was aberrantly increased in ovarian cancer tissues compared with NOSE or fallopian tube epithelium (FTE) tissues." (PMID 38424195, 2024). "Genetic alteration analysis of the TCGA pancancer cohort revealed that NSUN2 was amplified in various cancers, including ovarian cancer." (PMID 38424195, 2024). "Consistently, the m5C-hypermethylated RNAs in ovarian cancer cells tended to be downregulated upon NSUN2 knockdown, as determined by cumulative analysis." (PMID 38424195, 2024).
ovarian carcinoma (continued). "Consistently, our results revealed that several m5C modification genes were dysregulated in ovarian cancer, among which NSUN2 promoted ovarian cancer progression through regulating cell proliferation and metastasis, as we demonstrated." (PMID 38424195, 2024). "We subsequently collected fresh ovarian cancer tissues and FTE tissues to assess the protein expression of NSUN2 in ovarian cancer." (PMID 38424195, 2024). "Intriguingly, we found that NSUN2 protein expression decreased following E2F1 knockdown when we investigated the function of E2F1 in ovarian cancer cells." (PMID 38424195, 2024). "In this study, we found that the methyltransferase NSUN2 gene was amplified and upregulated in ovarian cancer and that NSUN2-induced RNA methylation facilitated the malignancy of ovarian cancer." (PMID 38424195, 2024). "The subcutaneous tumorigenesis assay showed that NSUN2 overexpression facilitated tumor growth from ovarian cancer cells." (PMID 38424195, 2024). "The results showed that multiple m5C regulators were dysregulated in ovarian cancer, among which the RNA methyltransferase NSUN2 exhibited the most dramatic alteration in expression, which was typically upregulated." (PMID 38424195, 2024). "Given that NSUN2 has been demonstrated to catalyze m5C modification of mRNA21, we first examined the localization of NSUN2 in ovarian cancer cells by immunofluorescence staining." (PMID 38424195, 2024). "E2F1 upregulates NSUN2 expression by activating its transcription, suggesting that genetic regulation and transcriptional regulation synergistically contribute to NSUN2 upregulation in ovarian cancer." (PMID 38424195, 2024). "Scientists have discovered that a gene named NSUN2, often found in excess in ovarian cancer, is vital for the cancer’s growth." (PMID 38424195, 2024). "To confirm this, we further performed E2F1 ChIP assays in ovarian cancer cells following NSUN2 knockdown." (PMID 38424195, 2024). "To determine the specific mRNA m5C modification mediated by NSUN2, we mapped the transcriptome-wide alterations in m5C modification at single-base resolution in ovarian cancer cells following NSUN2 knockdown via RNA-BisSeq." (PMID 38424195, 2024). "We identified 16,536 m5C peaks in 6912 RNAs in control ovarian cancer cells compared with the corresponding NSUN2-knockdown cells." (PMID 38424195, 2024). "Taken together, these results demonstrate the oncogenic role of NSUN2 in ovarian cancer through the regulation of cell growth and metastasis." (PMID 38424195, 2024). "Considering that YBX1 and NSUN2 regulate E2F1 expression in ovarian cancer, we examined the role of YBX1 in ovarian cancer." (PMID 38424195, 2024). "In this study, we revealed the crucial functions of NSUN2-mediated m5C modification of mRNAs in ovarian cancer." (PMID 38424195, 2024). "The links between NSUN2-mediated RNA modification and transcriptional regulation by E2F1 prove the complexity of regulatory network underlying the malignancy of ovarian cancer." (PMID 38424195, 2024). "To examine the effect of NSUN2 on the ability of cells to form secondary tumors in the peritoneal cavity, we injected NSUN2-defective and control ovarian cancer cells into the peritoneal cavity." (PMID 38424195, 2024). "We found that knockdown of E2F1 substantially suppressed the proliferation and metastasis of ovarian cancer cells, whereas re-expression of E2F1 in NSUN2-deficient cells mitigated the suppressive effect of NSUN2 knockdown on cell proliferation and metastasis." (PMID 38424195, 2024). "In conclusion, our study revealed that the RNA methyltransferase NSUN2 is highly expressed in ovarian cancer and predicts a poor prognosis." (PMID 38424195, 2024). "To further explore the role of upregulated NSUN2 in ovarian cancer, we established two NSUN2-knockdown stable clones in ovarian cancer cell lines A2780 and SKOV3." (PMID 35280737, 2022).
ovarian carcinoma (continued). "Then, we examined the expression levels of NSUN2 in a set of clinical samples and found that NSUN2 mRNA was highly expressed in ovarian cancer tissues (n = 20) compared to normal ovary tissues (n = 11)." (PMID 35280737, 2022). "Consistent with upregulation of gene expression, the protein level of NSUN2 was also increased in ovarian cancer." (PMID 35280737, 2022). "In ovarian cancer, an NSUN2/IGF2 signature has been identified, which has prognostic survival value, as patients with high NSUN2 expression and low IGF-II expression had significantly superior overall and disease progression-free survival." (PMID 32708015, 2020). "Then, we depleted NSUN2 in ovarian cancer cells by using shRNAs." (PMID 38424195, 2024). "Moreover, the copy number of NSUN2 was correlated with its expression level in ovarian cancer, indicating that the increased expression of NSUN2 in ovarian cancer is partially due to NSUN2 gene amplification." (PMID 38424195, 2024). "Conversely, NSUN2 overexpression increased mRNA m5C modification in ovarian cancer cells." (PMID 38424195, 2024). "Additionally, a subcutaneous tumorigenesis model and a peritoneal metastasis model were used to assess the oncogenic role of NSUN2 in ovarian cancer in vivo." (PMID 38424195, 2024). "Collectively, these results support a potential tumor-promoting role for NSUN2 in ovarian cancer." (PMID 38424195, 2024). "Furthermore, Kaplan‒Meier analysis revealed that increased expression of NSUN2 was strongly correlated with poor prognosis, as indicated by the results of overall survival and progression-free survival analyses of ovarian cancer patients." (PMID 38424195, 2024). "Furthermore, we constructed a tissue microarray containing 27 NOSE and 134 ovarian cancer specimens and found that NSUN2 protein expression was significantly upregulated in ovarian cancer tissues compared with NOSE tissues." (PMID 38424195, 2024). "We next sought to verify the other targets transcriptionally regulated by NSUN2 in ovarian cancer." (PMID 38424195, 2024). "In ovarian cancer cells, NSUN2 knockdown resulted in altered expression of 1744 genes, and RIP-seq revealed that NSUN2 could bind to 2842 transcripts." (PMID 38424195, 2024). "First, we overexpressed NSUN2 in ovarian cancer cells, namely, A2780, OVCAR3, and SKOV3 cells." (PMID 38424195, 2024). "Taken together, these results suggest that the overexpression of NSUN2 in ovarian cancer may be an incidental event." (PMID 35280737, 2022). "In addition, NSUN2 knockdown decreased PARP10 expression in ovarian cancer cells (Fig. EV4J,K)." (PMID 41326692, 2026). "NSUN2 is amplified, and its amplification is correlated with its increased RNA expression, which might be the trigger for the formation of the positive loop in ovarian cancer cells compared to normal ovarian epithelial cells." (PMID 38424195, 2024). "Collectively, these data demonstrate that NSUN2 establishes CDS-specific m5C marks on LGR4 mRNA to enable ALYREF recognition, thereby promoting cisplatin resistance in ovarian cancer." (PMID 41345330, 2025). "We found that knockdown of NSUN2 reduced m5C deposition on mRNA in both A2780 and OVCAR3 ovarian cancer cells." (PMID 38424195, 2024). "To determine the regulatory effect of NSUN2 on E2F1, we measured E2F1 protein expression upon NSUN2 knockdown in ovarian cancer cells." (PMID 38424195, 2024). "E2F1 affects NSUN2 transcription by interacting with the NSUN2 promoter, thus suggesting that NSUN2 and E2F1 form a positive feedback loop in ovarian cancer." (PMID 38424195, 2024). "In ovarian cancer, NSUN2 and YBX1 are amplified and upregulated, and higher expression of NSUN2 and YBX1 predicts a worse prognosis for ovarian cancer patients." (PMID 38424195, 2024). "In this study, we revealed that the RNA methyltransferase NSUN2 facilitates mRNA m5C modification and forms a positive feedback regulatory loop with the transcription factor E2F1 in ovarian cancer." (PMID 38424195, 2024).